CD4 (CD4 molecule)
Diseases named in the same sentence as CD4 in open-access papers (continued):
Sharing a sentence is not in itself a finding about the gene and the disease.
tumor (continued). "Unlike conventional αβ TcR+ CD4+ or CD8+ T cells, which recognize antigen-derived peptides, these cells recognize metabolic products derived from bacteria or tumor cells." (PMID 36875124, 2023). "In the non-irradiated left tumor, we observed a reduction in the percentage of CD3+, CD4+, and CD8+ T cells after PDT in the ineffective group." (PMID 36944686, 2023). "We used CyTOF to assess tumor-resident T cells in tumors ± GCSF secretion and found that virtually all signaling was reduced in the absence of tumor GCSF, with a significant decrease in pSTAT5 in both CD4+ and CD8+ T cells, and pSTAT3 in CD4+ T cells." (PMID 36911097, 2023). "The proportion of tumor-infiltrating CD8 T cells was no significantly change, and tumor-infiltrating CD4+T cells was significantly decrease by treatment with As-T combination therapy." (PMID 38161697, 2023). "NACT significantly increased infiltrates of CD4+Foxp3+ Treg cells (P = 0.036) and PD-L1+CD68+ macrophages (P = 0.022) in the stroma and decreased M1/M2 ratio (P = 0.016) in the tumor of CRS1 non-responders." (PMID 36993949, 2023). "The tumor cells were weakly positive for CD68 and lysozyme, negative for CD163, and positive for CD4, which excluded rare tissue cell-derived tumors." (PMID 36871023, 2023). "It was also noted that the levels of PMN‐MDSCs and Mo‐MDSCs subsets in MDSCs and the levels of CD4+ T and CD8+ T subsets in CD3+ T cells did not change in PBMCs of tumor‐bearing mice treated with NU7441." (PMID 36373232, 2023). "Most participants showed an enhancement in tumor-specific CD8+ and CD4+ T-cell responses, which did not correlate with increased levels of IL-12." (PMID 37886952, 2023). "A total of 7 d after Ad.dT or Ad.P60 i.t. injection, we did not observe differences in the content of the CD4+ and CD8+ populations in spleen or the tumor." (PMID 37766222, 2023). "The number of CD4+, CD8+ effector T cells, NK cells and DCs with anti-tumor effects are reduced, and they present nonfunctional status or immature phenotypes." (PMID 37064113, 2023). "Depletion of CD4+ or CD8+ T cells in untreated and OV-EGFP-treated tumor-bearing TgMISIIR-TAg-Low mice had practically no antitumor effects, consistent with the absence of TAg-specific TALs in peritoneal cavities in these mice." (PMID 36875325, 2023). "CD4 and CD8 densities were lower in the NEC segment than in the AC and ENT segments, and PD-L1 expression was negative throughout the tumor." (PMID 37027114, 2023). "While liver metastases contain lower levels of immune cells as already noted, both CD4 and CD8 T cells showed high correlations between primary tumors and metastatic samples within the tumor core, but not in other regions." (PMID 37768208, 2023). "Firstly, athymic nude mice, lacking T cell populations including CD4+ and CD8+ T cells, were utilized to investigate the impact of tumor-T cell interaction on tumor growth." (PMID 37545523, 2023). "Though the tumor cell lines used in this study do not express MHC class II, there are previous reports of the importance of CD4+ T cells and MHC class II-restricted neoepitopes in preclinical cancer immunotherapy." (PMID 37244905, 2023). "Through reclustering, we refined lymphoid cells such that the Tc cell cluster split into a Cd4-positive CD4 circulating cluster and a bona fide CD8 cluster negative for Cd4, which was locally depleted in dKO tumours." (PMID 37605008, 2023). "Although counts of skin infiltrating CD4+ and CD8+ T cells increased, no statistical significance was found post-tumor injection in the Treg depletion group." (PMID 37407600, 2023). "A poor OS was associated with non-operated patients [HR, 3.42 (1.15–10.16)] with low tumor MSLN expression [HR, 2.58 (1.09–6.10)], high levels of PD-L1, and low infiltration of T cells CD4+ in the TME [HR, 3.81 (1.58–9.18)]." (PMID 37901248, 2023). "In the spleens of tumor-bearing mice, we observed significantly elevated CD38+ cells in FoxP3 negative CD4+ T cells." (PMID 36757800, 2023).
tumor (continued). "Specifically, Kaplan–Meier survival analysis revealed a significantly better survival of patients with high CD3+ (DFS, P=0.0014; OS, P=0.0031) and CD4+ (DFS, P=0.0101; OS, P=0.0106) signals in the tumor region, but not with biomarker in the IM." (PMID 37090736, 2023). "The findings revealed a positive correlation between BCAS3 expression and B cells, CD4+ cells, and dendritic cells, while a negative correlation was observed with CD8+ cells and macrophages in the tumor immune cell infiltration of HNSCC patients (p<0.05)." (PMID 38259392, 2023). "The REP protocol preferentially expanded small clones of the CD4+ phenotype (CD4, IL7R, KLRB1) in the TME, indicating that the largest exhausted T cell clones in the tumor do not expand during the expansion protocol." (PMID 37484198, 2023). "While most preclinical studies on CXCR3 ligand–targeting therapeutic compounds indicate that CXCR3 ligand expression promotes the recruitment of CXCR3+ CD4+ and CD8+ T cells to the tumor site, other studies have suggested that this is not the case." (PMID 38104126, 2023). "CD8+ and CD4+ T cells predominantly consisted of effector memory T (Tem; CD45RA-CD62Llow) cells regardless of the tumor entity." (PMID 37532709, 2023). "In the mouse tumor model, it was reported that TNFR2 agonistic antibodies induced the expansion of CD4+ Tcon cells without affecting the Treg number in vivo." (PMID 37662935, 2023). "Our data indicated that CD4+ and CD8+ T lymphocytes did not play a critical role in vaccine-mediated protection against MDV-induced tumor development." (PMID 36992357, 2023). "Intravital two-photon microscopy demonstrated that eGFP+ TRP-1 CD4+ T cells preferentially arrested and engaged in long-lasting close interactions with CD11c-Venus+ immune cells only in HCmel12 CRISPR-ctrl tumours, but not in HCmel12 Trp1-KO tumours." (PMID 37316667, 2023). "In contrast, when MPP6 expression was “+++”, CD3+ T cells, CD4+ T cells and CD8+ T cells were mainly concentrated in the peritumoral stroma of HCC samples, with few or no T cells penetrating into the tumor parenchyma." (PMID 37207207, 2023). "In the tumor-draining lymph node (tdLN) and bone marrow, significantly higher frequencies of CD431B11+CD4+ T cells but not CD431B11+CD8+ T cells in the PDOX treated mice were detected, and these cells differentially expressed ICOS, CD38, CD39, and KLRG1." (PMID 36796366, 2023). "Although the anti-tumour response of CAR T cells is not within the natural MHC-II context of CD4+ T cells, it does clearly demonstrate the therapeutic potential of CD4+ CTLs as effector cells for anti-tumour immunotherapy." (PMID 37122720, 2023). "By depleting CD4 and CD8 T cells separately, our study showed that human CD4 T cells mediated potent tumor control independent of CD8 T cells, implying that CD4 CTLs can play a critical and non-redundant role in fighting particular HLA-II+ tumors." (PMID 37185301, 2023). "Depletion of CD4+ T cells, despite being present in the TME and having an activated phenotype, did not impact tumor control in PDOX-treated mice." (PMID 36796366, 2023). "Here we found that T-cells bearing second-generation CARs, which receive in vivo restimulation via a vaccine activating the CAR in lymph nodes, are capable of promoting robust host CD4+ and CD8+ T-cell responses against non-CAR-related tumor antigens." (PMID 37413990, 2023). "Analysis of splenocytes obtained from tumor-bearing animals revealed only insignificant changes in the number of B or T cells or macrophages, nor was there any effect on the CD8/CD4 ratio or the T cell activation status." (PMID 36915084, 2023). "To this end, we used our pipeline to assess the abundance of PBMCs positive/negative for CD4, CD8 and CD3 in the blood samples from the 30 tumor patients over the course of proton therapy." (PMID 38092866, 2023).
tumor (continued). "In preclinical models, dual blockade of TIM-3 and PD-1 restored the function of both CD4+ and CD8+ T cells and led to complete tumor regression whereas either monotherapy was not effective." (PMID 37928556, 2023). "Immunohistological results showed no changes in the numbers of CD4 + and CD8 + tumor-infiltrating lymphocytes (TILs) between oxamte plus CAR-T combination and CAR-T alone groups." (PMID 37770937, 2023). "There was no decrease observed in the total number of transferred CD4+ T cells (CFSE+CD3+CD4+), indicating a specific inhibition of Treg migration in the tumor of MIP treated group." (PMID 37122749, 2023). "In line with this, we observed that tumours isolated from mice treated with RANO alone for 21 d expressed higher levels of Cd45, Cd3g and Cd8; a similar trend was observed with Cd4, which did however not reach significance." (PMID 37563469, 2023). "We demonstrate that CD8 T cells induced by tumor implantation are superior to CD8 T cells induced by a vaccine at preventing secondary tumor growth, and that this concomitant tumor immunity is dependent on CD40L and can occur independent of CD4 T cells." (PMID 37072485, 2023). "Although the anti-tumor activity of the CD4/HLA-II axis has generally been attributed to its helper function in boosting CD8 CTLs, direct tumor-targeting by CD4 T cells has not been examined closely." (PMID 37185301, 2023). "Treatment with PD-1 antibody increased the activation of CD8+ T cells and the numbers of CD4+ and CD8+ TEF cells in Shp2f/f, but not in Shp2f/fLysMCre tumor-bearing mice, which had more TEF cells in dLN in both IgG2a and PD-1 Ab treatment groups." (PMID 36581713, 2023). "The use of a Gal-1-targeting DNA aptamer (AP-74 M-545) prevented the binding of Gal-1 to CD45 and increased CD4+ and CD8+ T cell influx, suppressing tumour growth in immunocompetent but not in immunocompromised mice." (PMID 36817445, 2023). "More importantly, we discovered an over-representation of CD4+ memory T cells expressing inhibitory receptors in omental fat of PC patients, but not in their blood or adipose tissue of non-PC patients, which suggests local anti-tumour immunity might be compromised." (PMID 37580610, 2023). "The results clearly indicated that depletion of CD8+ T cells compromised the anti-tumor effect of LR-DPVB, while depletion of CD4+ T cells did not exert a significant impact on tumor progression." (PMID 38001101, 2023). "Depletion of CD4+ T helper cells did not change the response to i.t. poly(I:C), while depletion of CD8+ cytotoxic T cell completely abrogated the anti-tumor response." (PMID 37467718, 2023). "Taken together, these results demonstrates that CD4, but not CD8 T cells are required to control tumor growth." (PMID 37185301, 2023). "The results showed that IGFBP1 expression had a weak positive correlation with B cell infiltration, while it had a weak negative correlation with STAD tumor purity, CD8 + T cell, CD4 + T cell, macrophage, neutrophil, and dendritic cell." (PMID 37000073, 2023). "Following implantation, tumor size was determined using bioluminescent IVIS imaging and mice were then assigned to treatment groups of either 1:1 CD4+:CD8+ human HER2 CAR T cells or negative control Empty Vector (EV) human T cells." (PMID 37152812, 2023). "There was also no strong correlation between the PD-L1 expression in bulk tumour and the proportion of CD3+, CD4+ and CD8+ cells in post-expansion TIL cultures." (PMID 35158816, 2022). "Assessment of tumor samples for lymphocyte infiltration (CD3, CD4, CD8, and CD79a) revealed no distinguishable differences between treated and untreated samples." (PMID 35834467, 2022). "Wherein the armed BsAb strategy provided potent decreases in the rate of tumor growth and trafficked increased TIL, the addition of LIGHT imparted actual tumor regressions and increased not only CD8+ TIL, but also CD4+ TIL, which BATs alone did not." (PMID 35177811, 2022).
tumor (continued). "LAG-3 is frequently co-expressed with PD-1 on activated CD4- and CD8-positive tumor-infiltrating T-cells, and is known to be a negative regulator of T-cell function." (PMID 36289918, 2022). "We revealed that tumor-treated SC significantly up-regulated the expression of CD73 and PD-1 on CD8+ and CD4+ T cells up to 5–6 times but did not alter the expression of CD39 on T cells." (PMID 36428970, 2022). "IHC showed that CD3 and CD4 were protective proteins, while PD1 and PD-L1 in tumor cells were negative proteins." (PMID 36263183, 2022). "Previous research has often focused on CD8+ cytotoxic T cells, however, CD4+ T cells have gained attention in the field, as they are not only essential to promote help to CD8+ T cells, but are also able to kill tumor cells." (PMID 36249757, 2022). "Patients showed an increase in tumor infiltrating CD3+, CD4+ and CD8+ lymphocytes and no serious adverse effects related to G207 administration." (PMID 35155581, 2022). "In both CD4+ and CD8+ populations, the proportion of T-bet+ cells had a strong negative correlation with the proportion of PD-1+ cells (CD4+: r = −0.66; CD8+: r = −0.67), suggesting that there is a TIL population with anti-tumour characteristics." (PMID 35158816, 2022). "Immunohistochemical analysis verified a profound reduction in the number of tumor-infiltrating CD8+ T cells, but not CD4+ T cells, in Whsc1-depleted CT26 xenografts and in the polyps of Apcmin/+Whsc1IEC–/– mice compared with that seen in Whsc1-intact lesions." (PMID 35230972, 2022). "Fifth, our study only confirmed the relationship between YTHDF1, YTHDF2, CD4, CD8, and FOXP3, however did not reveal which pathway YTHDF1, YTHDF2 affects on the tumor immune profile." (PMID 36479088, 2022). "In conclusion, tumor immunity was different according to the neoadjuvant therapy method and response, with CD86, CD4, and t/iCD8 expression, but not CTLA-4 and sCD8 expression, being significantly higher in the nCT-treated and poor response groups." (PMID 36428666, 2022). "This is in accordance with the lack of correlation between CD4+CD25+ Foxp3+ infiltrating Tregs and the tumor volume both in lean and obese mice." (PMID 35472214, 2022). "This phenotypic alteration was specific, as it was noted that tumor-exosome treatment did not alter expression of CD3, CD4, CD8, CD56, or CD16." (PMID 35031075, 2022). "The frequencies of both OVA‐specific CD4+ and CD8+ CD44+ effector and CD44+ CD62L+ memory T cells normalized per gram of tumor weight in the SVF SPH+amDC‐transplanted group were significantly higher than those in control groups." (PMID 36058002, 2022). "In similar studies involving CD4+ T cell depletion using the GK1.5 mAb, there was no change in protection provided against tumor growth by the EO771 WCV suggesting a limited role of CD4+ T cells in this particular anticancer vaccine." (PMID 36139558, 2022). "After RH-Δcps treatment, with the increase of tumor-specific CD8+ T cells and CD4+ T cells in tumors, the IFN-γ level increased 5- to 10-fold in tumor, but there is no significant change in the whole body." (PMID 36118042, 2022). "In our scRNA-seq analyses among tumor TILs from HPV+ HNSCs, we did not observe a difference in PA transport gene set expression between Tregs and CD4+ CTL, CD4+ TCM, or CD4+ TEM cells." (PMID 36052016, 2022). "In the present study, we compare the co-expression of PD-1 on CD4, CD8, and CD56 tumor-infiltrating cells, and PD-L1 on tumor cells between HIV-infected and non-HIV-infected groups." (PMID 35311077, 2022). "Hence, the amount of T cells CD8, T cells CD4 memory activated, NK cells activated were positively relevant to the expression level of HLA-DRB1, suggesting that HLA-DRB1 expression may be closely related to the maintenance of anti-tumor immune activity of the TME." (PMID 36129956, 2022).
tumor (continued). "CD4+ T cell depletion completely ablated the tumor control efficacy of the NBTXR3 + XRT + PLT therapy, resulting in tumor growth and survival curves virtually indistinguishable from those of untreated controls." (PMID 36123677, 2022). "IHC staining results indicated that the deletion of ALKBH5 significantly increased the number of tumor-infiltrating CD3+, CD4+, and CD8+ T cells but not in the FOXP3+ cells." (PMID 36566230, 2022). "The results showed that CCL17 and CD3G (CD4/CD8+ T cell marker molecule), CD4 (CD4+ T cell marker molecule), and CD79B (naive B-cell marker molecule) were expressed to some extent in tumor tissues of three LUAD patients without dysregulation." (PMID 35321241, 2022). "The log-rank test showed that the distance between CD4+/CD8+ T cells and tumor cells were not related to RFS." (PMID 36685566, 2022). "Lastly, the Immunoscore index significantly correlated with tumor infiltration of T cell subsets, including CD3, CD4, CD8 and regulatory T cells (Tregs), but not with myeloid cell subsets in pre-treatment ZUMA-1 biopsies." (PMID 36038629, 2022). "In contrast to myeloid cell analysis, no significant changes in the percentage of CD4+, CD8+, NK, and NKT cells after multiparameter cytometric analysis of lymph nodes (analogous to tumor tissue analysis) were revealed." (PMID 35372586, 2022). "Cross-presenting conventional Type 1 DCs are indispensable for the anti-tumor, but not anti-viral, T cell response, and type I IFN-dependent CD4+ Th1 effector cells contribute to optimal anti-tumor immunity." (PMID 36418317, 2022). "In murine models, treatment with VISTA antibodies increases the number of CD4 + and CD8 + tumor specific T cells in the TME and converts non-functional/exhausted CD8 + T cells to functional T cells." (PMID 36058945, 2022). "In our experiments, UBE2I expression was positively correlated with purity and inversely with CD4+ T cells, MP, NP, and DC rather than CD8+ T cells, regardless of tumor stages." (PMID 36193060, 2022). "There was no statistical difference in percentages of CD8+T, CD4+T, CD3+CD56+, NK, B cells, and monocytes between tumor, paratumor, and MNG tissues, nor between the peripheral blood from PTC and MNG patients." (PMID 36420264, 2022). "CD4 production of IFNγ, and not TNFα or CD40L, is required for the reeducation process and tumor rejection." (PMID 35903540, 2022). "Tumor cells in NKCL were consistently negative for CD3, CD4, and CD5 and showed moderate CD2, CD38, CD56, and CD94 and heterogeneous expressions of CD7, CD8, CD16, and CD26." (PMID 35299754, 2022). "FC did not correlate with any of the markers of local tumour inflammation (Klintrup–Mäkinen grade, lymphocytes, neutrophils, CD3, CD4, CD8, CD45, TIA-1, granzyme B and myeloperoxidase)." (PMID 35397505, 2022). "CD4+ and CD8+ T cells showed an increased frequency in the tumor but not in the spleen while nonsignificant trend was observed for CD19+ B cells." (PMID 35110563, 2022). "APCs also activate CD4+ T-cells similarly to CD8+ T-cells, except that the tumor antigen epitope is displayed on MHC-II rather than MHC-I." (PMID 36560420, 2022). "To evaluate the tumor microenvironment, we performed flow cytometric analysis in CT26 xenografts and found decreased infiltration of CD8+ T cells but not CD4+ T cells or macrophages in Whsc1-deleted CT26 tumors." (PMID 35230972, 2022). "In the tumour drainage lymph nodes (TDLNs) of the combination group, there was a 18% reduction in CD8+IFN‐γ+ T cells and a 0.47% reduction in CD4+CD25+FOXP3+ regulatory T cells, as opposed to 5.0% and 5.1% reductions, respectively, for the control group." (PMID 35174623, 2022). "TUBA1B was overexpressed in NSCLC PBL T cells, C14 CD4/CD8 T cell clusters, and activated tumor Tregs of CD4-C9-CTLA4 (TNFRSF9+) vs. non-activated tumor Tregs of CD4-C9-CTLA4 (TNFRSF9−)." (PMID 35804895, 2022).